EGFR (epidermal growth factor receptor)
Diseases named in the same sentence as EGFR in open-access papers (continued):
Sharing a sentence is not in itself a finding about the gene and the disease.
tumor (continued). "Binding of bCet and biotinylated Panitumumab (bPan) to tumor cells, correlated with the number of cell surface EGFR molecules and biotinylated Rituximab (bRit) did not bind." (PMID 25238453, 2014). "Tumor imaging probes for human epidermal growth factor receptor 2 (HER2), epidermal growth factor receptor (EGFR), and vascular endothelial growth factor (VEGF), which are the target molecules of trastuzumab, cetuximab/panitumumab, and bevacizumab, respectively, have been developed." (PMID 25365349, 2014). "Although EGFR is overexpressed and p27Kip1 is down-regulated in many human cancer types, the molecular interplay between the growth promoter and the tumour suppressor had not been explored." (PMID 25121353, 2014). "The authors have showed that erlotinib - an epidermal growth factor receptor inhibitor - is not able to kill tumor cells, but it leads them into a quiescent state or decreases their proliferation rate." (PMID 25184361, 2014). "EGFR positivity among tumors was extremely heterogeneous, whereas we did not observe major intra-tumour differences in HER-2 expression." (PMID 24454858, 2014). "In addition, the staining intensity of p-EGFR and p-AKT in the tumor cells was significantly decreased compared with the control (P<0.05)." (PMID 25289091, 2014). "Our study was not designed to detect the presence of EGFR wild type subclones however, if this wild type tumor cell population exists, it is not an obstacle to initial EGFR molecular diagnosis defined by the qualitative presence of the EGFR mutation." (PMID 24885034, 2014). "Accordingly, we presumed that further improvements might come from the findings of new target, the overcoming of EGFR-TKIs tolerance and the combination of EGFR-TKI with chemotherapy since the mechanisms of their anti-tumor activity are different." (PMID 25474307, 2014). "Preclinical studies with U3-1287 demonstrate tumor inhibition in A549 model and partial inhibition in FaDu model, suggesting the antibody might be more effective against HER2+/EGFR+ amplified models relative to the NRG driven models." (PMID 25400118, 2014). "To further determine whether CHIP decreases the EGFR expression and inhibits tumor growth, we performed immunohistochemistry to detect the expression of CHIP, EGFR and Ki67 in nude mice tumor tissues." (PMID 24722501, 2014). "In different HNSCC models simultaneous radiotherapy and cetuximab leads to heterogeneous effects on local tumor control, potentially correlating with genetic EGFR amplification but not with EGFR expression." (PMID 24603603, 2014). "To strengthen our hypothesis, we determined the role of EGFR in mediating EMT and CK expression on the MCF7 tumor cell line that possesses epithelial characteristics." (PMID 25277187, 2014). "However, we could not predict EGFR mutation status by the GGO proportion of nodules or tumor size." (PMID 24885886, 2014). "Suppression of anti-tumor immunity was reversed by the addition of anti-TGF-β antibody or COX-2 inhibitor, supporting the rationale for inhibition of TGF-β and COX-2 pathways to overcome potential immunosuppressive effects due to EGFR inhibition." (PMID 25240937, 2014). "In addition, TBK1-II cooperated with lapatinib, a EGFR/HER2 inhibitor, to accelerate apoptosis in vitro and suppress tumor growth in a xenograft model of HER2+ BC." (PMID 25594009, 2014). "Additionally for five tumor regions of BI15 that were subjected to light-whole genome sequencing, EGFR copy number estimates were consistent between whole genome sequencing and smMIP techniques." (PMID 25608559, 2014). "Mutations in EGFR result in activation of the PI3K/AKT pathway and the survival of tumor cells without affecting tumor cell proliferation." (PMID 24410791, 2014).
tumor (continued). "Consequently, inhibiting autophagy with chloroquine significantly enhanced tumor cell death induced by gefitinib and AKT inhibitors in EGFR M+ cells in vitro, and produced greater tumor shrinkage in EGFR M+ xenografts in vivo." (PMID 24946858, 2014). "The authors formulated oleic acid-coated MNPs assembled with cationic lipid shells, and functionalized them with an appropriate siRNA sequence to knock down the epidermal growth factor receptor (EGFR) mRNA, as it is overexpressed in tumor blood vessel endothelium." (PMID 25077142, 2014). "A modulation of PD biomarkers in terms of downregulation of EGFR, AKT and CDK4 client proteins was achieved either in vitro, on A431 tumor cells treated with SST0116CL1, and in terms of down-modulation of c-Met, AKT and CDK4 ex vivo in tumor lesions collected from GTL-16 tumor-bearing mice." (PMID 25096516, 2014). "Recent trials have shown that patients with KRAS mutant tumours do not respond to anti-EGFR agents (cetuximab/panitumumab) because the activating mutation occurs downstream from the target of anti-EGFR therapy." (PMID 25361007, 2014). "Nevertheless, we observed that EGFR inhibitors resulted in decreased anti-tumor responses, regardless of upregulation of HLA-DR expression on the tumor cell." (PMID 25240937, 2014). "AKT activation has been reported in 51% of NSCLC patient samples and 74% of NSCLC cell lines, suggesting that combining EGFR and AKT inhibition may increase anti-tumor activity and prevent the occurrence of resistance to EGFR TKIs." (PMID 24946858, 2014). "Ten patients (3 EGFR positive) had only a surgical treatment of the primary tumour and CNS was the first site of disease progression in 5 patients, none of them EGFR positive." (PMID 24991207, 2014). "Both the primary tumor and metastasis displayed cells with 7p polysomy; however, the metastasis also contained regions of high-level EGFR amplification not observed within any region of the primary tumor." (PMID 25164765, 2014). "This pattern of RTK amplification has been observed for PDGFRA and EGFR, and targeting either receptor is not sufficient to eliminate the tumor making necessary a combined treatment." (PMID 24473088, 2014). "Thus, our findings uncover the PHD3-dependent regulation of EGFR as a novel mechanism, extending the range of PHD3 targets to a new signalling pathway with a key role in tumor progression." (PMID 25420773, 2014). "In addition, a significantly higher number of tumours expressing HER-3 (P = 0.037), or co-expressing EGFR/HER-3 (P = 0.035), or HER-3/HER-4 (P = 0.026) were found in tumours <pT4 stage in this study." (PMID 24609222, 2014). "Both Iressa (an EGFR targeted anti-tumor drug) treatment and PI4KIIα knockdown inhibited MCF-7 tumor growth, which is consistent with our previous results showing that downregulation of PI4KIIα results in nearly complete inhibition of MCF-7 cell-induced tumor growth in vivo." (PMID 24801752, 2014). "Enhanced drive for expression of IL-6 and IL-11 may also be due to increased ligand driven EGFR activation, which also signal via STAT3, and which show increased expression during active tumour growth in the gp130757FF mouse." (PMID 24804649, 2014). "Immunohistochemistry showed the tumor cells always negative for epidermal growth factor receptor (EGFR)." (PMID 24559248, 2014). "Unlike known oncogenes such as HER2 and EGFR, EpoR mRNA is not elevated when tumor samples are compared with normal samples." (PMID 24337485, 2014). "Undoubtedly, gefitinib and erlotinib have powerful anti-tumor activity and are superior to chemotherapy in patients with advanced non-squamous NSCLC with EGFR mutations." (PMID 25050082, 2014). "Therapeutically, only the dual targeting of HER2 and EGFR by combining a small-molecule inhibitor, such as the dual EGFR/HER2 inhibitor lapatinib, with a moAb, such as cetuximab or pertuzumab, induced overt and long-lasting tumor regressions in proof-of-concept trials in HER2-amplified xenopatients." (PMID 24811491, 2014).
tumor (continued). "Immune regulatory cytokine TGF-β has been reported to mediate the resistance to EGFR inhibition, however, direct activity of EGFR mediated TGF-β production from tumor toward antitumor immune cells has remained largely unknown." (PMID 25240937, 2014). "The local tumour control data are comparable to previous experiences where an inhibition of tumour growth by EGFR-TK inhibitors did not translate into an improvement on local tumour control in different tumour models." (PMID 25444177, 2014). "Because erlotinb is a tyrosine kinase inhibitor that targets EGFR and CHIP might target EGFR for degradation, we sought to investigate the synergistic effect of CHIP and erlotinb on tumor apoptosis." (PMID 24722501, 2014). "Additional approaches such as repeated cycles of RIT, conjugation to α-emitting radionuclides, or chemo-RIT combinations with inhibitors of EGFR signalling, cell cycle checkpoints, or DNA repair, may contribute to eradication of LL2 tumours." (PMID 24387284, 2014). "In human tumor xenograft models that expressed or overexpressed HER family members, AST1306 showed antitumor activities, especially against those with HER2 overexpression or EGFR T790M mutant tumors." (PMID 24612546, 2014). "For these 22 adenocarcinomas, we analyzed different tumor area, displaying similar or different architectural patterns and no EGFR heterogeneity was seen within these specimens." (PMID 24885034, 2014). "Based on the importance of EGFR in SCCHN progression, we hypothesized that Dacomitinib would effectively reduce tumor viability and enhance IR cytotoxicity in SCCHN models." (PMID 24853121, 2014). "CXCR2 was proposed to be involved in the tumour malignancy via EGFR-dependent mechanism 46, while CXCL8 might play a potential role in tumour development by EGFR transactivation." (PMID 24268047, 2014). "Factors associated with early progression under EGFR-TKI might be predictive of EGFR-TKI resistance, or prognostic, related to tumor aggressiveness." (PMID 24408092, 2014). "Unfortunately, neither chemotherapy nor EGFR-TKI treatment produced effective tumor response in this patient." (PMID 24885608, 2014). "In addition, microvesicles can accurately model the profile of the tumor cell including changes in IDH-1, EGFR, and EGFRvIII." (PMID 25312641, 2014). "Recent studies suggest that EGFR amplification and activation are correlated with invasive/non-angiogenic tumor growth." (PMID 25058589, 2014). "Concerning specimens with very low tumor cell content (≤10%, n = 25), 5 were found wild type and 2 were non informative, none of these 7 specimens had an increased EGFR CN." (PMID 24885034, 2014). "All HER-2 negative cases were also negative for EGFR expression, whereas a subset of EGFR-negative tumours was found among HER-2 positive tumours." (PMID 24454858, 2014). "Patients with EGFR expressing tumors did not respond to EGFR-targeted therapy, which suggests that EGFR expression alone does not indicate tumor cell growth dependence on the EGFR pathway." (PMID 24886365, 2014). "Clinically, patients with KRAS wild-type tumours are more likely to respond to anti-EGFR therapy whereas those with mutant KRAS show lack of benefit." (PMID 24720724, 2014). "In agreement with previous observations, EGFR expression was frequently detected in tumor tissue but not in normal tissue." (PMID 24945674, 2014). "While the ability of Erlotinib to increase the anti-tumor effect of etoposide in mammospheres could be attributed to its potential to inhibit MDR proteins, it could also exert its anti-EGFR and anti-topoisomerase activity." (PMID 25472619, 2014). "Addition of the tumor-reactive anti-EGFR antibody cetuximab did not further improve the anti-tumor activity of activated M1-like macrophages." (PMID 24612598, 2014). "We observed that secretion of TGF-β and PGE2 by the HNSCC cells was increased following EGFR inhibition, despite a lack of evident changes in immune costimulatory molecules or EGFR expression in tumor cells." (PMID 25240937, 2014).
tumor (continued). "So far KRAS is the only potential biomarker for predicting the efficacy of anti-EGFR therapies in CRC, since KRAS mutant tumours do not respond to anti-EGFR agents." (PMID 25361007, 2014). "Likewise, hypoxic stress enables the epidermal growth factor receptor (EGFR) to phosphorylate Ago2 and prevent its binding to Dicer, thereby inhibiting the processing and maturation of tumor suppressive pre-miRNAs (e.g., miR-31, miR-192, and mir-193-5p;)." (PMID 25717380, 2014). "Cetuximab (monoclonal antibody for EGFR) was unable to decrease cell migration and showed no dose dependent decrease in cell migration in all 4 tumor cell lines." (PMID 24638075, 2014). "The binding of EBP50 to the epidermal growth factor receptor (EGFR) and neurofibromin 2 (NF2) may also result in tumor suppression." (PMID 25120624, 2014). "Although the difference was not statistically significant (P>0.05), this may be interpreted as a linear relationship between tumor size and HER-2 activity as EGFR is a known activator of cancerous cell growth." (PMID 24303437, 2013). "The binding experiments were conducted using tumor tissues slices identified by pathology examination as EGFR positive and slices of adjacent normal colonic mucosa tissues, located close to the tumor that were identified as EGFR negative." (PMID 23857061, 2013). "Our data suggest the presence of false-negative cases within the EGFR WT results, obtained from the cytological specimens with a small number of tumor cells (even up to 1,000)." (PMID 23817662, 2013). "Other antibody-targeted liposome formulations, including anti-HER2 and anti-EGFR liposomes, accumulate in the tumor at levels similar to non-targeted liposomes." (PMID 24009717, 2013). "While Case 3 did not have a detected EGFR exon 19 deletion, it is unlikely that if we had available primary tumor tissue, this deletion would be detected." (PMID 24171005, 2013). "Contrary to this result, another EGFR inhibitor, erlotinib, showed little anti-tumor activity and no synergistic effect upon co-treatment with sorafenib in a rat model of HCC." (PMID 23785399, 2013). "When used in second or advanced line setting, cetuximab as monotherapy appears to have minimal activity in metastatic GC and GEJ cancers although again tumor expression of EGFR was not required to participate in these trials." (PMID 24216699, 2013). "It is possible that EGFR and STAT3, individually or as a pair, contribute to tumor progression." (PMID 24499623, 2013). "In all, 460 patients with KRAS wild-type tumours who had not previously received EGFR therapy were randomly allocated to irinotecan (230 patients) or IrPan (230 patients), and these form our primary population for this report." (PMID 23725851, 2013). "In invasive HNSCC tumor, overexpression of EGFR was observed in 84% (37/44) samples irrespective of tumor stages." (PMID 23675485, 2013). "IgA2 EGFR was also effective in WT SCID mice indicating that its anti-tumour effects in this model were largely independent of FcαRI Tg, suggesting the involvement of Fab-mediated anti-tumour effects." (PMID 23918228, 2013). "Apart of its role in tumor pathogenesis, MET/HGF deregulated function emerges as an important resistance mechanism to targeted therapies against other oncogene systems such as that of the epidermal growth factor receptor (EGFR)." (PMID 24378750, 2013). "Furthermore, P276-00 inhibited expression of soluble proteins such as IL-6, EGFR and HSPA8 that promote tumor microenvironment." (PMID 23414419, 2013). "We found that simultaneous inhibition of EGFR and VEGFR2 signaling pathways with delphinidin may offer greater anti-tumor efficacy for advanced NSCLC than inhibitors of either pathway alone." (PMID 24124611, 2013). "Available tumor from the sigmoid colon was tested for an EGFR exon 19 deletion, and an exon 19 deletion was not identified." (PMID 24171005, 2013).
tumor (continued). "All selected tumor lines (TCG2, TCG3, and TCG4) were characterized by high basal phospho-EGFR expression, along with phospho-AKT and phospho-MEK overexpression, supporting the activation of the EGFR signaling pathway in tumors." (PMID 23874590, 2013). "However, only EGFR mutations were tested in 112 patients, neither KRAS nor EGFR mutation test could not be done in 32 patients due to small amount of tumor DNA, and 11 cases who were not tested for both exon 19 and 21 EGFR mutations were classified as unknown mutation status." (PMID 23724098, 2013). "For example, in a study on patients with EML4-ALK translocations a lack of tumor response to EGFR TKI was reported." (PMID 23922984, 2013). "By contrast, the cobas EGFR test does not require macrodissection unless the estimated tumor content in the specimen is below 10%." (PMID 23621958, 2013). "We looked for correlations of EGFR amplification and/or NFKBIA deletion and overall survival (OS): four GBM were excluded from analysis as the patients died early after diagnosis for reasons unrelated to tumor progression." (PMID 24330732, 2013). "Analysis of the original patient tumor and xenografts revealed that although a copy number gain was detected for the whole chromosome 7, where EGFR is located, the EGFR locus was not significantly amplified (data not shown)." (PMID 24260133, 2013). "We previously reported that, in NSCLC patients, HGF is present mainly in cancer cells with acquired resistance to EGFR-TKIs, suggesting that HGF may be produced predominantly in resistant tumor cells via an autocrine mechanism." (PMID 24386407, 2013). "In our case, analysis of the patient’s tumor and xenografts demonstrated that, although a copy number gain was detected for chromosome 7, the EGFR locus was not significantly amplified." (PMID 24260133, 2013). "Despite efficient cell binding, however, GrB-T released from activated NKL/GrB-T cells did not facilitate killing of EGFR-overexpressing tumor cells in the absence of an exogenous endosomolytic activity." (PMID 23573299, 2013). "Furthermore, it has been noted that therapeutic antibodies that target EGFR may induce antibody-dependent, cell-mediated cytotoxicity, resulting in an indirect beneficial effect owing to the recruitment of cytotoxic immune cells such as monocytes and natural killer cells to the tumor." (PMID 24199171, 2013). "Analysis of human GBM biopsies confirmed that EGFR activation correlated with invasive/non-angiogenic tumor growth." (PMID 23429996, 2013). "Unfortunately, neither the usual molecular markers (EGFR amplification, PTEN loss) nor the basal overexpression of phosphoproteins were useful to distinguish this responsive tumor." (PMID 23874590, 2013). "By contrast, our results displayed significantly decreased mRNA content of EGFR transcripts in tumor tissue compared to mucosa tissue without significant changes at the protein levels of EGFR." (PMID 24171795, 2013). "Based on our previous experiments we assume that the signal we measured in EGFR Exon 18 did not depend on the tumor cell content." (PMID 24039832, 2013). "Mounting evidence indicates that ErbB4, unlike EGFR or ErbB2, functions as a tumor suppressor in many human malignancies." (PMID 24791013, 2013). "Sometimes we cannot acquire genotypes of EGFR and other genes by reasons of tumor sample or technology unavailable in clinical." (PMID 23383079, 2013). "Transcript analysis alone, however, would not reliably predict the functionally relevant EGFR agonist released by tumor-primed mononuclear cells." (PMID 23597096, 2013). "Dok2 KO mice without EGFR expression displayed many fewer tumor nodules at this age than C/EGFRDEL mice, indicating that Dok2 loss likely cooperates in a synergistic manner with oncogenic EGFR." (PMID 24255704, 2013). "COX-2 and EGFR proteins showed a positive correlation in mucosa, while a negative correlation occurred in tumor tissue." (PMID 24171795, 2013).